FLRT2 (fibronectin leucine rich transmembrane protein 2)
Diseases named in the same sentence as FLRT2 in open-access papers (continued):
Sharing a sentence is not in itself a finding about the gene and the disease.
giant cell bone tumor (1 paper, 2023). "FLRT2 gene expression is regulated by miRNA and is associated with the pathogenesis of giant cell bone tumor." (PMID 37090697, 2023).
Granuloma (1 paper, 2025). A compact, organized collection of mature mononuclear phagocytes, which may be but is not necessarily accompanied by accessory features such as necrosis. "Given the involvement of mTORC1 signaling in the differentiation of foamy macrophages during M. tuberculosis infection, Flrt2 may contribute to foamy macrophage differentiation in necrotizing granulomas." (PMID 40843005, 2025). "Furthermore, we identified Flrt2, Hyal1, and Mmp13 as novel molecular markers of Plin2-expressing macrophages, which were localized to the peripheral rim regions of necrotizing granulomas." (PMID 40843005, 2025).
granulomatosis with polyangiitis (1 paper, 2012). A small-vessel necrotizing vasculitis characterized by the association of inflammation of the vessel wall and peri- and extravascular granulomatosis. "Anti-FLRT2 activities were detected in nine (10.2%) of 88 patients with SLE and one (6.7%) of 15 patients with granulomatosis with polyangiitis (Wegener's)." (PMID 22747982, 2012).
Huntington disease (1 paper, 2018). Huntington disease (HD) is a rare neurodegenerative disorder of the central nervous system characterized by unwanted choreatic movements, behavioral and psychiatric disturbances and dementia. "What is more, cortical pathology present in Huntington’s disease, may have its molecular onset in downregulation of FLRT2 gene, which is one of the neural development regulators and is responsible for regulation of cortical neurons migration during brain development." (PMID 30713489, 2018).
ischemic stroke (1 paper, 2023). A stroke disorder caused by obstruction of blood flow to the brain, due to thrombotic (local blood clot formation) or embolic (due to a blood clot or other material traveling from another site) event. "Altered DNA methylation of the TRIM6, TLN2, and FLRT2 genes may play a functional role in ischemic stroke in Chinese populations." (PMID 37370144, 2023).
Listeria monocytogenes infection (1 paper, 2023). "In addition, in vivo investigation of the vital roles of FLRT2-regulated myelopoiesis in disease models, such as Listeria monocytogenes infection or myeloid leukemia, is needed in our future study." (PMID 37090697, 2023).
myeloid leukemia (1 paper, 2023). A clonal proliferation of myeloid cells and their precursors in the bone marrow, peripheral blood, and spleen. "Using qPCR and immunoblot analyses, we confirmed a dramatical FLRT2 increase in PMA-differentiated THP-1 cells, as well as HL-60 (a human myeloid leukemia cell line) cells." (PMID 37090697, 2023).
Stroke (1 paper, 2023). Sudden impairment of blood flow to a part of the brain due to occlusion or rupture of an artery to the brain. "In this study, we found that stroke patients exhibited lower methylation level of the FLRT2 gene compared to controls." (PMID 37370144, 2023). "However, findings from our CRISPR/dCas9-Dnmt3a cell model suggest that the observed DNA methylation changes have antagonistic effects suggesting that we identified a mixture of stroke inducing (e.g., TRIM6 gene) as well as neuroprotective (e.g., TLN2 and FLRT2 genes) epigenetic biomarkers." (PMID 37370144, 2023).
uterine cancer (1 paper, 2024). Primary or metastatic malignant neoplasm involving the uterine corpus and/or the cervix. "Finally, possible association of FLRT2 down-regulation with the process of ovarian and uterine cancers due to downregulated expression has been suggested." (PMID 39149564, 2024).
tumor (19 papers, 2017 to 2026). "For instance, our study showed that the overexpression of NUAK1, LRRC17, FOXM1, and CDC20 as well as the downregulation of FLRT2 are associated with DNA repair pathway as well as tumor invasion pathways." (PMID 39149564, 2024). "FLRT2 (Fibronectin Leucine Rich Transmembrane Protein 2) was identified as a tumor suppressor in a global study on epigenetic regulations and biological functions." (PMID 39654143, 2024). "This study revealed that FLRT2 acted as a tumor suppressor by inhibiting cancer cell stemness in NSCLC." (PMID 39444619, 2024). "FLRT2 overexpression inhibited, while FLRT2 silence facilitated tumour cell growth, migration and invasion." (PMID 37480224, 2023). "Fibronectin leucine rich transmembrane protein 2 (FLRT2) is related to the regulation of the progression of various tumors, including BC, as a tumor suppressor gene." (PMID 37886960, 2023). "Of note, transcriptome sequencing data also showed that Flrt2 expression was significantly higher in alveolar macrophages of tumor-bearing mice than in normal mice." (PMID 37090697, 2023). "In contrast, a recent study reveals that FLRT2 promotes cancer aggressiveness by mediating tumor-specific interendothelial adhesions." (PMID 37090697, 2023). "Yet, emerging evidences have indicated that FLRT2 also participates in regulating tumour progression." (PMID 37480224, 2023). "The FLRT2 is highly expressed in tumor neovascularization and forms abnormal endothelial adhesion to prevent oxidative stress of cells." (PMID 36845724, 2023). "It is reported that downregulated expression of FLRT2 was observed in CRC tumor samples compared to matched normal epithelial mucosa." (PMID 35805033, 2022). "Endothelial cell–specific deletion of Flrt2 in mice selectively pruned abnormalized vessels, resulting in a unique metabolic state termed “oxygen-glucose uncoupling,” which suppressed tumor metastasis." (PMID 35104247, 2022). "In combination with the clinical data, these data indicate that FLRT2 is expressed by endothelial cells lining tumor vessels that are exposed to high levels of oxidative stress." (PMID 35104247, 2022). "Similar to the transient effect of VEGF blockade during the ‘‘normalization window’’, deletion of endothelial Flrt2 increased the tumor-suppressing effects of a cytotoxic agent, cisplatin, and those of immunotherapeutic drugs (anti-PD1 antibodies)." (PMID 35104247, 2022). "Because the placenta produces ROS and is exposed to oxidative stress, we sought to examine expression of FLRT2 in abnormalized tumor vessels, which are also exposed to oxidative stress." (PMID 35104247, 2022). "Taken together, these results define a tumor-suppressor role of FLRT2 with epigenetic silencing in the pathogenesis of CRC." (PMID 33193897, 2020). "Among the 16 cases of CRC tumor samples with down-regulated FLRT2 expression, 13 cases exhibited FLRT2 methylation." (PMID 33193897, 2020). "Further clinical relevance analysis revealed that methylation of FLRT2 is closely associated with tumor differentiation, lymphatic metastasis in CRC patients, which strongly indicated that FLRT2 methylation is also involved in CRC progression." (PMID 33193897, 2020). "In vitro experiments showed that FLRT2 functions as a tumor suppressor in CRC by suppressing cell proliferation and cell colony formation, and inhibiting migration and invasion." (PMID 33193897, 2020). "In conclusion, our findings define that FLRT2 was a putative tumor suppressor in CRC and a potential biomarker for CRC diagnosis and therapeutic applications." (PMID 33193897, 2020). "In conclusion, our findings highlight a tumor-suppressive role of FLRT2 in CRC progression, probably by regulating AKT and ERK signaling pathway." (PMID 33193897, 2020). "The top pathway was “Cellular growth and proliferation”, or “Cancer”-related function, with the majority of the genes deregulated in a direction pointing to FLRT2 as a potential tumor suppressor." (PMID 28325946, 2017).
tumor (continued). "A set of genes related to movement and adhesion of tumor cell lines were differentially expressed after FLRT2 regulation." (PMID 28325946, 2017). "Taken together, our results provide insights into the role of FLRT2 as a novel tumor suppressor in the breast, which is inactivated by hypermethylation during tumor development." (PMID 28325946, 2017). "Our findings support the notion that FLRT2 functions as a tumor suppressor in NSCLC." (PMID 39444619, 2024). "Some studies have reported FLRT2’s role in tumor development." (PMID 39444619, 2024). "Such a result could corroborate the fact that FLRT2 gene and protein expressions were higher in normal tissue than in tumor tissue." (PMID 39596804, 2024). "The difference in the function of FLRT2 during development and tumor angiogenesis may be ascribed to differential expression of its receptors." (PMID 35104247, 2022). "Homophilic binding of FLRT2 constitutes tumor-specific interendothelial adhesion." (PMID 35104247, 2022). "This protocol effectively deleted Flrt2 from the tumor endothelial cells." (PMID 35104247, 2022). "Deletion of Flrt2 prevents tumor metastases and spontaneous tumor formation." (PMID 35104247, 2022). "Endothelial Flrt2 sustains abnormalized tumor vessels in mice." (PMID 35104247, 2022). "However, of 6 cases of CRC tumor samples with up-regulated FLRT2 expression, only one cases displayed methylation." (PMID 33193897, 2020). "We further clarified that FLRT2 might act as a tumor suppressor which suppressed cell growth and migration through mediating PI3K/AKT and ERK signaling pathways." (PMID 33193897, 2020). "Furthermore, FLRT2 overexpression demonstrated antitumor effects in a xenograft tumor mouse model." (PMID 39444619, 2024). "However, FLRT2 methylation state was highly related to tumor stage and metastasis." (PMID 33193897, 2020). "The results indicated that AIFM3, HSH2D, and PTPN6 were significantly up-regulated, while DCHS1, PTGIS, FLRT2, PCSK5, and CLSTN2 were significantly down-regulated in tumor samples compared with normal samples." (PMID 34512722, 2021). "To explore the function of FLRT2, we first compared its expression in tumour with matched normal tissues using the BLCA public database." (PMID 37480224, 2023). "The data above indicate that the deletion of endothelial Flrt2 efficiently suppresses tumor angiogenesis without triggering metabolic reprogramming." (PMID 35104247, 2022). "Deletion of endothelial Flrt2 in mice selectively ablated these abnormalized vessels, thereby suppressing tumor invasion and metastasis without triggering the metabolic switch." (PMID 35104247, 2022). "Healthy vessels outside the tumor, postnatal retinal vascularization, and wound healing were not affected by Flrt2 deletion." (PMID 35104247, 2022). "Deleting Flrt2 from endothelial cells selectively pruned those abnormalized vessels, leading to uncoupled provision of oxygen and glucose and resulting in reduced tumor intravasation and metastasis without triggering metabolic reprogramming." (PMID 35104247, 2022). "Subsequently, the expression level of FLRT2 was further examined in 22 CRC tumor samples and matched normal epithelial mucosa." (PMID 33193897, 2020). "Furthermore, multivariate analyses using a Cox proportional hazards model revealed that high expression of FLRT2 by endothelial cells was an independent risk factor for RFS, regardless of tumor stage." (PMID 35104247, 2022).
cancer (14 papers, 2017 to 2024). A tumor composed of atypical neoplastic, often pleomorphic cells that invade other tissues. "In this study, we investigated the regulatory role of FLRT2 in cancer cell stemness in NSCLC and the underlying mechanism." (PMID 39444619, 2024). "One of the genes screened in silico, FLRT2, showed hypermethylation and downregulation in the cancer dataset and the association was verified both in cultured cell lines and cancer patients’ tissue." (PMID 28325946, 2017). "The association between methylation and expression of FLRT2 was further analyzed using 713 cancer data from the TCGA breast database, which observed a close association (R = −0.128, P < 0.001)." (PMID 28325946, 2017). "Other studies revealed that Flrt2 could be used as a cancer signature gene to estimate risk stratification in early-stage stomach cancer and prostatic adenocarcinoma (PRAD) patients." (PMID 37090697, 2023). "Among potentially cancer-associated methylated genes identified, FLRT2 was one of top-ranked." (PMID 33193897, 2020). "Overall, our findings demonstrated that FLRT2 was downregulated in NSCLC tissues and cancer cells, and upregulation of FLRT2 inhibited the stemness and tumorigenesis of NSCLCCSC." (PMID 39444619, 2024). "As the stemness of cancer cells is a major cause of drug resistance, both bioinformatics analysis and IC50 value detection exhibited that FLRT2 abrogates NSCLC cells cisplatin resistance." (PMID 39444619, 2024). "Meanwhile, we found that FLRT2 overexpression also significantly inhibited the migrative and invasive capacities of the two cancer cells." (PMID 37480224, 2023). "The highest burden of 3′ UTR mutations are found in FLRT2 and LPP (mutated in 20 and 15 patients, respectively), which are both cell adhesion proteins associated with cancer." (PMID 37516102, 2023). "According to the GEO data, promoter methylation of FLRT2 appeared to be higher in cancer of grade I~III than in the normal breast tissue." (PMID 28325946, 2017). "Of note, the IPA network analysis in the normal and cancer cell line where FLRT2 was ectopically dysregulated identified cancer-related pathways in common, suggesting that FLRT2 is closely involved in carcinogenesis." (PMID 28325946, 2017). "In contrast, upregulation of FLRT2 in MCF-7, a cancer cell line that expresses FLRT2 at a lower than normal level, showed decreased proliferation, confirming anti-proliferation activity of FLRT2." (PMID 28325946, 2017). "FLRT2 expression increased in all the examined cancer cell lines except for HCC38 following treatment of 5-Aza-2′-deoxycytidine." (PMID 28325946, 2017). "NEDD4 increases cancer stemness, FLRT2 abrogates the NEDD4-induced NSCLC progression." (PMID 39444619, 2024). "Interestingly, FLRT2 was expressed abundantly in CD34+ endothelial cells within areas of progression in stage IV cancer samples, but far less so in superficial areas." (PMID 35104247, 2022). "This suggests a possible relationship between FLRT2 and cancer metastasis." (PMID 28325946, 2017). "So far, little is known about the epigenetic regulation as well as expression of FLRT2 in cancer." (PMID 28325946, 2017). "The results indicated that the gene expression of ADAM12, FLRT2, and SLIT2 was higher in ER alpha-positive cancers." (PMID 39596804, 2024). "Fibronectin Leucine-Rich Transmembrane Protein 2 (Fibroleukin, FGA) and NOTCH3, known for their roles in muscle adptation and cancer progression, are particularly intriguing in this context." (PMID 39130639, 2024). "Cell-surface proteases, such as ADAM12, VNN1, and FLRT2, would cleave ECM components with the aid of SLIT2, CYR61, and ADAM12 in response to mechanical stimuli, allowing for cancer cells to migrate more easily." (PMID 39596804, 2024). "Out of 52 genes investigated, we observed that many genes upregulated in M2 and downregulated in M1 macrophages–ACTN1, FLRT2, MRC1, PTGS1, RHOJ, TMEM158–correlated positively with the EMT scores (first 6 rows) across multiple cancer types." (PMID 30729096, 2019).
cancer (continued). "The expression of many genes that induce adhesion, such as CXCR4 and DCN, and cellular movement in cancer, such as DKK1 and ITGB4, evidently increased when FLRT2 was downregulated, and decreased when FLRT2 was upregulated." (PMID 28325946, 2017). "Moreover, we found that FLRT2 expression was significantly lower in NSCLC cells and even lower in NSCLC stem cells, indicating that FLRT2 may suppress cancer cell stemness in NSCLC." (PMID 39444619, 2024). "In addition, while there was no detectable expression of FLRT2 in normal colon tissues or stage I tumors, strong expression was observed in progressive areas of stage II, III, and IV tumors, which are defined as advanced cancers." (PMID 35104247, 2022).
FLRT2 also shares sentences with these, for which no sentence is quoted: abortion (1 paper); Arrhythmia (1); autoimmune disease (1); cardiac insufficiency (1); COVID-19 (1); depression (1); Fanconi anemia (1); focal epilepsy (1); glioma (1); hyperlipidemia (1); microphthalmia (1); neurological diseases (1); psychiatric disorder (1); rectum adenocarcinoma (1); renal cell carcinoma (1); retinal degeneration (1); rheumatoid arthritis (1); schizophrenia (1); spinal cord injury (1).